TLR2 (toll like receptor 2)
Diseases named in the same sentence as TLR2 in open-access papers (continued):
Sharing a sentence is not in itself a finding about the gene and the disease.
Myocardial fibrosis (7 papers, 2012 to 2024). "Previous studies have shown that TLR2 is associated with myocardial fibrosis." (PMID 36225554, 2022). "In DOX-induced rats, miR-143 reduced cardiac dysfunction, myocardial apoptosis, myocardial fibrosis, TLR2 levels, and pyroptosis." (PMID 39018487, 2024). "TLR2 has been shown to play a key role in cardiovascular disease, and knockdown or inhibition of TLR2 with neutralizing antibodies in mice attenuated Ang II-induced myocardial fibrosis." (PMID 38727300, 2024). "In summary, we demonstrated that NOX1 promoted myocardial fibrosis and cardiac dysfunction via activating the TLR2/NF-κB pathway in diabetic cardiomyopathy." (PMID 36225554, 2022). "In brief, these data suggest that NOX1 promotes myocardial fibrosis in diabetic cardiomyopathy by activating the TLR2/NF-κB pathway." (PMID 36225554, 2022). "In summary, we demonstrated that NOX1 induced activation of the TLR2/NF-κB pathway and increased reactive oxygen species production accumulation, which ultimately increased myocardial fibrosis and deteriorated cardiac function in diabetic cardiomyopathy." (PMID 36225554, 2022). "The upregulation of NOX1 expression promoted myocardial fibrosis through the activation of the TLR2/NF-κB pathway." (PMID 36225554, 2022). "To clarify the role of the TLR2 signaling pathway in DCM myocardial fibrosis, we investigated TLR2 and its ligand NF-κB on gene transcription and protein expression levels in cardiac tissues." (PMID 36225554, 2022). "In rats, cardiac function, serum levels of cardiac enzymes, apoptosis, myocardial fibrosis, and levels of IL-1β, IL-18, TNF-α, TLR2, and pyroptosis-related molecules were detected." (PMID 39018487, 2024). "Blocking TLR2, but not TLR4, activity not only reduced mortality, but also attenuated doxorubicin-induced cardiac dysfunction by 20% and inhibited myocardial fibrosis." (PMID 22808256, 2012).
osteomyelitis (7 papers, 2010 to 2024). An acute or chronic inflammation of the bone and its structures due to infection with pyogenic bacteria. "It has been reported that aureus peptidoglycan promotes osteoclast formation through TLR2-mediated activation of the nuclear factor kappa-B (NF-κB)/nuclear factor of activated T cells 1 (NFATc1) signaling pathway, causing bone destruction and the formation of osteomyelitis." (PMID 39301021, 2024). "In the majority of patients with implant-associated osteomyelitis, however, T cells expressing TLR1, TLR2 or TLR4 were detected." (PMID 21151520, 2010). "The association between TLR2 polymorphisms and vulnerability to osteomyelitis and this signaling pathway, however, has not been proven." (PMID 39301021, 2024). "Recently, it was reported that the natural flavone myricetin presents anti biofilm activity against Staphylococcus aureus and attenuates osteomyelitis by inhibiting the Toll-like receptor-2 (TLR2)/mitogen-activated protein kinase (MAPK) pathway in experimental mice." (PMID 37764304, 2023). "Similarly, Baicalein attenuated osteomyelitis by inhibiting Toll-like receptor 2 (TLR2) and MAPK signaling in Staphylococcus aureus-treated mice and MC3T3-E1 cells." (PMID 36839278, 2023). "A more detailed analysis revealed that some of the S. aureus isolates lacking host TLR2-activity were small colony variants (SCV), others were obtained from chronic infections such as osteomyelitis or endocarditis." (PMID 24810614, 2014).
Peri-Implantitis (7 papers, 2019 to 2024). An inflammatory process with loss of supporting bone in the tissues surrounding functioning DENTAL IMPLANTS. "Our data showed that the levels of TLR2, TLR4, IRAK1, and TRAF6 gene expression were in agreement with that in bone loss, suggesting peri-implantitis augmented by glycemic fluctuation were at least partly mediated through the activation of TLR2/4 signaling." (PMID 34401982, 2021). "Our present study showed that anti-RANKL antibody can significantly inhibit the bone loss in peri-implantitis and additional miR-146a treatment will enhance this inhibition through its anti-inflammation effects via TLR2/4 signaling." (PMID 32291538, 2020). "Our previous studies showed that TLR2 are associated with implant bone loss in a mouse model of peri-implantitis and TLR4 is essential for periodontal bone loss." (PMID 32291538, 2020). "Consistent with our results, a recent research shows that TLR2 knockout can alleviate bone loss and inflammatory infiltrate in peri-implantitis mouse models." (PMID 31623650, 2019). "A recent research also demonstrates the crucial role of TLR2 signaling activation in exacerbated bone loss and inflammatory infiltrate in peri-implantitis." (PMID 31623650, 2019). "This study suggests that glycemic fluctuation may aggravate peri-implantitis inflammation and bone loss, which may be associated with a shift in peri-implant microbial profile towards dysbiotic changes and the activation of TLR2/4-IRAK1-TRAF6 signaling." (PMID 34401982, 2021). "Drawing on strategies used in developing tumor vaccines, researchers have attempted to target CXCR4 (a receptor for TLR2) to create an immunotherapeutic agent for peri-implantitis." (PMID 39555067, 2024). "This process indicates that RANKL plays a pivotal role in the pathogenesis of peri-implantitis and is regulated by TLR2, LOX-1, and Erk1/2 signaling in response to P. gingivalis infection." (PMID 39555067, 2024). "Previous research has explored the therapeutic effect of anti-RANKL antibody (500 μg/mL) with or without microRNA 146a (miR-146a) (100 nM) towards C57/BL6 wild-type (WT) mice and TLR2-/-TLR4-/- (TLR2/4 KO) peri-implantitis mice models." (PMID 39555067, 2024). "Taken together, miR-146a in addition to anti-RANKL antibody can further reduce bone loss in WT mice but is ineffective when TLR2 and TLR4 are deficient, suggesting miR-146a anti-bone loss effects in peri-implantitis are TLR2/4 dependent." (PMID 32291538, 2020). "Due to the heterogeneity in lipid A structure, LPS from some pathogens in peri-implantitis can interact with TLR2 and subsequently activate TLR2 downstream pathways, contributing to the production of numerous proinflammatory cytokines, including IL6." (PMID 31623650, 2019). "Our results showed that TLR2 expression levels were in agreement with the severity of peri-implantitis." (PMID 31623650, 2019). "TLR2 (Toll-like receptor 2) signaling and its downstream proinflammatory cytokines are considered to be important in the progression of peri-implantitis." (PMID 31623650, 2019). "In the present study, we determined the effects of changing glycemic conditions on TLR2/4 signaling and pro-inflammatory cytokines levels in peri-implant tissues, and on the subsequent bone resorption, using an experimental peri-implantitis diabetic murine model." (PMID 34401982, 2021). "Taken together, anti-RANKL antibody alone did not affect inflammatory cell infiltration in peri-implantitis, and miR-146a showed anti-inflammatory effects only on WT mice but not on TLR2/4-deficient mice." (PMID 32291538, 2020). "Upon mangiferin treatment, TLR2 expression decreased in mice with peri-implantitis." (PMID 31623650, 2019). "Additionally, the expression of TLR2 protein was greater in all mice with peri-implantitis (P and M mice) than in N mice, whereas it obviously decreased in mice with peri-implantitis upon mangiferin treatment (M mice vs. P mice)." (PMID 31623650, 2019).
Peri-Implantitis (continued). "Additionally, our results indicate that excellent glycemic control might attenuate peri-implantitis through inhibiting TLR2/4 signaling." (PMID 34401982, 2021). "Thus, suppressing the activation of TLR2 signaling may become an effective strategy for peri-implantitis therapy." (PMID 31623650, 2019). "Based on the findings, downregulating TLR2 and TLR4 in cells is the most direct and effective method for controlling peri-implantitis." (PMID 39555067, 2024). "In summary, the co-regulation of RANKL expression by TLR2, LOX-1, and Erk1/2 signaling pathways represents a novel strategic approach for treating peri-implantitis." (PMID 39555067, 2024). "As newly discovered triggers of the inflammatory pathway, TLR2 and LOX-1 can mediate RANKL production, making them potential therapeutic targets for treating peri-implantitis." (PMID 39555067, 2024). "However, little is known about the functions of TLR2 and TLR4 signaling in peri-implantitis." (PMID 32291538, 2020). "In this work, we demonstrate the inhibition of TLR2, NFκB p65, p38, and JNK activation in experimental peri-implantitis upon mangiferin treatment, but it still remains to be confirmed whether there are other members in these inflammatory protein families involved." (PMID 31623650, 2019).
pulmonary aspergillosis (7 papers, 2010 to 2025). "Both the protective (at 0.1 mg/kg) and the exacerbating (at 5 mg/kg) effects of caspofungin were lost in TLR2 deficient mice, indicating that TLR2 is required for the antifungal activity of echinocandins against aspergillosis." (PMID 24672516, 2014). "An attractive approach would be to investigate whether common genetic variations that slightly alter TLR2 function are associated with detrimental IL-17-mediated inflammation in aspergillosis." (PMID 28904353, 2017). "Of note, several polymorphisms of human TLRs, e.g., TLR1, TLR2, TLR4, TLR6, or TLR9, have been associated with increased risk of invassive aspergillosis in susceptible hosts." (PMID 29081774, 2017). "This occurred through epithelial cell–released S100B that paracrinally inhibited the TLR2–dependent activity of recruited PMNs, a finding consistent with the ability of RAGE to impair neutrophil functions as well as with the down–regulated TLR2 activity in pulmonary aspergillosis." (PMID 21423669, 2011). "In pulmonary aspergillosis, TLR2 and TLR4 have no role in immunocompetent animals, although TLR2−/−and TLR4−/− are susceptible to invasive aspergillosis induced in immunosuppressed mice." (PMID 23255875, 2012). "In pulmonary aspergillosis, TLR2 and TLR4 have no role in otherwise immunocompetent animals, although Aspergillus CFU were elevated in vinblastin- or cyclophosphamide-treated TLR2−/−and TLR4−/− mice." (PMID 20617171, 2010).
Respiratory tract infection (7 papers, 2008 to 2023). An infection of the upper or lower respiratory tract. "Prevotella nigrescens, which elicits TLR2 signaling and p65-Mediated Inflammation, is an oral bacterial species causing for respiratory tract infections." (PMID 33681225, 2021). "Together, these results suggest that other – TLR2 independent - components of host defense are sufficient to maintain an adequate immune response during respiratory tract infection caused by S. pneumoniae." (PMID 22721450, 2012). "Therefore, in the present study we compared the response of TLR2 KO and wild-type (WT) mice during respiratory tract infection with WT and pneumolysin-deficient S. pneumoniae." (PMID 17711480, 2008). "Sham or C. muridarum respiratory tract infection was induced in neonatal Wt, TLR2−/−, 4−/− and 2/4−/− mice and weight gain and clinical score assessed over a 0–14 day time course." (PMID 22724018, 2012). "pneumoniae, establishing that TLR2 plays a modest role in the induction of a pulmonary inflammatory response to respiratory tract infection with WT S. pneumoniae." (PMID 17711480, 2008). "The cell wall components of S. aureus include lipid teichoic acid and peptidoglycans (both TLR2 ligands), which may stimulate the release of IL-17 via TLR2-related pathways during respiratory tract infection." (PMID 38022571, 2023). "Several MyD88 dependent TLRs are known to be important for the innate immune response to respiratory tract infection with K. pneumoniae, particularly TLR4 and TLR9, and during late stage infection or in the presence of high bacterial numbers, TLR2." (PMID 25254554, 2014).
systemic sclerosis (7 papers, 2016 to 2025). A chronic disorder, possibly autoimmune, marked by excessive production of collagen which results in hardening and thickening of body tissues. "The described trial revealed that among patients with systemic sclerosis, the rare TLR2 Pro631His variant is associated with antitopoisomerase positivity (the SSc diffuse manifestation) and the development of PAH." (PMID 41303627, 2025). "This speculation could be supported by the studies showing that TLR2 and its gene polymorphism were robustly associated with the increased levels of inflammatory mediators and development of PAH in patients with systemic sclerosis." (PMID 32860486, 2020). "TLR2- or TLR4-mediated stimulation was also reported to promote DCs to produce IL-10, induce an augmented Th2 immune response, and aggravate systemic sclerosis (SSc)." (PMID 35619184, 2022). "However, excessive activation of TLR2 or TLR4 in dFBs by endogenous DAMPs such as TLR4 ligands hyaluronan, fibrinogen, and other ECM proteins or TLR2 ligand serum amyloid A (SAA) may lead to the pathogenesis of fibrotic skin disorders, such as hypertrophic scarring and systemic sclerosis (SSc)." (PMID 31815151, 2019).
thrombosis (7 papers, 2015 to 2025). "A polymorphism in the toll-like receptor 2 (TLR2) has recently been linked to the pathogenesis of thrombosis in SLE patients." (PMID 25908929, 2015). "In particular, African Americans and European Americans show an association between TLR2 mutation and thrombosis." (PMID 25908929, 2015). "The release of histones from dying cells is associated with microvascular thrombosis, while blocking platelet TLR2 and TLR4 decreases the percentage of activated platelets and reduces the amount of thrombin generated, indicating that TLR2 and TLR4 mediate the activation process." (PMID 32645848, 2020). "Conversely, the inhibition of TLR2 diminished these effects, underscoring the critical role of the TLR2/NF-κB signaling pathway in the development of thrombotic disease following deep vein thrombosis." (PMID 40510367, 2025). "Further clinical studies correlating thrombosis incidence with TLR2 levels in a larger patient sample and extensive thrombosis panel investigations are necessary to confirm the significant involvement of TLR2 in thrombosis in MPN." (PMID 39157201, 2024). "Due to the significant association of TLR2 levels with Jak2 mutation and leukocytosis, which were reported to be associated with a higher incidence of thrombosis in MPN, studies were conducted to investigate platelet activation correlated with TLR2 levels." (PMID 39157201, 2024). "Thrombosis incidence was higher in TLR2-elevated patients (29%) than in TLR2-normal patients (19%)." (PMID 39157201, 2024). "Importantly, patients with elevated TLR2 levels experienced a higher incidence of thrombosis episodes, including both arterial and venous thrombosis (29%), compared to patients with normal TLR2 values (11%)." (PMID 39157201, 2024). "Recent research has shown that C29 markedly decreases the expression of inflammatory markers, including IL-6 and TNF-α, through the inhibition of the TLR2/NF-κB/COX-2 signaling pathway, which helps relieve traumatic deep vein thrombosis." (PMID 40510367, 2025).
urinary tract infection (7 papers, 2013 to 2024). "A screen of several common urinary tract infections (UTI)-related organisms showed strong induction of TLR2-signaling in the same assay." (PMID 29593720, 2018). "It seems that activation of the CD14/TLR2 and/or CD14/TLR4 pathway during the acute phase, which reflects the general activation of the immune system due to the underlying infection, may play an important role in the limitation of urinary tract infection." (PMID 27252945, 2016).
alcoholic liver diseases (6 papers, 2013 to 2024). A disorder caused by damage to the liver parenchyma due to alcohol consumption. "In the alcoholic liver disease, there is evidence that TLR2 deficiency significantly alleviates damage, while TLR3 deficiency, on the contrary, aggravates it." (PMID 39769138, 2024). "Modulation of TLR2 function affected inflammatory process in chronic hepatitis (B, C), nonalcoholic fatty liver disease and alcoholic liver disease." (PMID 36693049, 2023). "Regulation of TLR2 function affects the inflammatory process in alcoholic liver disease, viral liver disease and other liver diseases." (PMID 36693049, 2023). "Sera from alcoholic patients, but not from healthy controls, were able to stimulate TLR2- and TLR4-transfected HEK293 cells to secrete CXCL1, suggesting that CXCL1 up-regulation is dependent on soluble factors found in alcoholic liver disease, and involves TLR2 and TLR4 signaling." (PMID 24260493, 2013).
Anorexia (6 papers, 2016 to 2020). Lack of desire to eat (loss of appetite). "The anorexia and weight loss observed in Pam3CSK4-treated wild-type mice were completely rescued in TLR2 KO mice." (PMID 27405276, 2016). "Antagonists of nuclear factor kappa B (NF-κB), cyclooxygenase pathway and melanocortin receptors 3/4 reversed the anorexia and body weight loss induced by TLR2 activation." (PMID 27405276, 2016). "Consistent with the phenotypes of TLR2 KO mice, MyD88 deficiency dramatically reduced the Pam3CSK4-induced anorexia and body weight loss." (PMID 27405276, 2016). "Central administration of Pam3CSK4 resulted in an increase in α-MSH fibers in the hypothalamic PVN, further confirming that the melanocortin pathway may mediate central TLR2-induced anorexia and body weight loss." (PMID 27405276, 2016). "In this publication, the authors further showed that administrations of NF-κB or MC4R antagonists reversed the anorexia induced by TLR2 activation." (PMID 32024569, 2020). "Activation of TLR2 by intracerebroventricular injection of its ligand, Pam3CSK4, induced sickness behavior symptoms, including anorexia, hypoactivity, and hyperthermia." (PMID 31509519, 2019). "One study showed that stimulation of TLR2 by intracerebroventricular injection of the synthetic ligand Pam3CSK4 induced anorexia and increased IBA1-positive microglial density and structural contacts with proopiomelanocortin (POMC) neurons in the hypothalamic arcuate nucleus of mice." (PMID 29354029, 2017). "To more directly clarify the role of TLR2 in central nervous system (CNS)-controlled sickness behaviors, we centrally administered Pam3CSK4, a synthetic agonist of TLR2, and examined sickness behaviors including anorexia, hypoactivity, and hyperthermia." (PMID 27405276, 2016). "However, further experiments are required to determine whether this anorexia mediated by TLR2, which is likely a transient symptom of sickness behavior, shares pathogenic mechanisms with anorexia nervosa, which develops over months to years in humans." (PMID 29354029, 2017).
atrial fibrillation (6 papers, 2011 to 2023). A disorder characterized by an electrocardiographic finding of a supraventricular arrhythmia characterized by the replacement of consistent P waves by rapid oscillations or fibrillatory waves that vary in size, shape and timing and are accompanied by an irregular ventricular response. "Toll-like receptor 2 (TLR2) has recently been shown to be up-regulated in patients with non-valvular atrial fibrillation (AF)." (PMID 23554687, 2011). "In addition, platelets sampled from both the periphery and the left atrium had significantly higher levels of surface TLR2 expression in patients with atrial fibrillation (AF) compared to those without AF." (PMID 32858930, 2020).
bipolar disorder (6 papers, 2015 to 2025). A disorder of the brain that causes unusual shifts in mood, energy, activity levels and the ability to carry out day-to-day tasks. "Genotype frequencies of the studied TLR2 and TLR4 polymorphisms for the 531 bipolar disorder patients." (PMID 25790282, 2015). "Indeed we recently described genetic associations between TLR2 and TLR 4 “low expressor” genotypes and bipolar disorder." (PMID 26352598, 2015). "Interestingly, a study found that carriers of the TLR2 rs3804099 TT genotype may be more vulnerable to early stress and inflammation-mediated damage, potentially accelerating the earlier onset of bipolar disorder." (PMID 40558558, 2025).